STAT3 (signal transducer and activator of transcription 3)
Diseases named in the same sentence as STAT3 in open-access papers (continued):
Sharing a sentence is not in itself a finding about the gene and the disease.
tumor (continued). "The results here provide genetic evidence that these STAT3+ CAFs comprise a subpopulation crucial to the establishment of an environment permissive to tumor development and progression." (PMID 35803738, 2022). "It has been demonstrated that the lack of long-term antitumor efficacy of PARP inhibitor, Olaparib, is partially attributed to its activation of Signal Transducer and Activator of Transcription 3 (STAT3) in tumors and the tumor microenvironment." (PMID 36324587, 2022). "STAT3 supports tumor progression by interfering with a number of cancer-promoting activities, such as proliferation, migration and anti-estrogen resistance." (PMID 36291767, 2022). "STAT3 can promote the growth of tumor cells and play an important role in the occurrence and development of cancer." (PMID 35958524, 2022). "autophagy activated by RAGE promoted IL-6-induced STAT3 activation; in addition, downregulation of autophagic activity in RAGE-targeted knockout KC mice inhibited STAT3 activation and ATP generation in mitochondria and delayed tumor development." (PMID 35559037, 2022). "The role of Stat3 in cancer is controversial, with several studies demonstrating an oncogenic role in the development of various cancers, whereas others have indicated that Stat3 behaves as a tumor suppressor." (PMID 36017196, 2022). "These suppressive myeloid cells expressed high levels of MARCO activated by tumor derived IL-10 that was induced via the transcription factor STAT3." (PMID 36310582, 2022). "The STAT3-mediated signalling cascade is one of these, and it is a necessary mediator of tumour-induced immunosuppression for immune cell activation." (PMID 36157880, 2022). "Activation of Janus kinase (JAK), signal transducer, and STAT3 pathway promotes tumor growth, angiogenesis, and survival." (PMID 36551991, 2022). "Consistently, S1P–S1PR1 signaling in tumor cells or the tumor microenvironment induced persistent STAT3 activation and IL-6 production, leading to tumor growth and metastasis." (PMID 35565311, 2022). "It has been demonstrated that the blockade of aberrant STAT3 signaling induces tumor cell apoptosis and inhibits tumor growth, confirming its critical role in the molecular pathogenesis of several tumors." (PMID 38938528, 2022). "Remarkably, our data are coherent with the crucial role of persistently activated STAT3 in increasing tumor cell proliferation, survival and invasion while suppressing anti-tumor immunity." (PMID 35805156, 2022). "IL-6 also activates the Janus kinase (JAK) signal transducer and activator of the STAT3 (signal transducer and activator of transcription 3) pathway, leading to adverse effects in tumours, such as reduced apoptosis in HCC cells." (PMID 35572649, 2022). "The expression and phosphorylation of STAT3 beta (STAT3β), which is an isoform of STAT3 has tumor-suppressive activities in MLL-AF9 AML." (PMID 34741119, 2022). "In conclusion, our study revealed that decreased expression of Wip1 was correlated with a higher rate of tumour metastasis and chemoresistance and increased ascites volume, and Wip1 negatively regulated angiogenesis through the STAT3-VEGF signalling pathway." (PMID 35538489, 2022). "Stimulation of the IL-6 / JAK / STAT3 pathway in cancer cells modulates the expression of several genes involved in the proliferation, survival and transformation of tumor cells." (PMID 35948877, 2022). "The dependence on aberrantly active STAT3 to support tumor cell growth and survival is well established." (PMID 36473850, 2022). "Gal‐3 is also expressed in tumor tissues in a HIF-1α-dependent manner, causing an increase in PD‐L1 level via STAT3 phosphorylation in carcinomas." (PMID 36071472, 2022).
tumor (continued). "While several members of the STAT family are involved in malignancies, however, a few members which include STAT3 and STAT5 are linked to tumor initiation and progression." (PMID 35401182, 2022). "STAT3 is constitutively phosphorylated in GBM cancer stem cells (GSCs) and inhibiting STAT3 phosphorylation attenuates GSC‐driven tumour growth, showing that STAT3 plays a critical role in GBM tumorigenesis." (PMID 35670018, 2022). "It was also proposed that TNF-α-induced TNFR2 expression triggers the proliferation of CRC cells and intestinal epithelial cells by stimulating the signal transducer and activator of transcription-3 (STAT3) protein for tumor promotion." (PMID 35954156, 2022). "Consistent with previous studies, DDR can lead to the production of cancer-related inflammation, which induces TME-secreting factors such as TNF, IL-1, CCL2, and CXCL8; and activates transcription factors of NF-Κb, Stat-3, thus promoting tumor proliferation." (PMID 35413945, 2022). "The activation of REG3A will enhance JAK2/STAT3 pathway, amplify the carcinogenic effect of IL-6/JAK2/STAT3, and ultimately leads to excessive PC cell proliferation in vitro and in vivo and tumor formation." (PMID 36591515, 2022). "The persistent and aberrant activation of specific STAT factors, particularly STAT3, often results in the growth and survival of tumor cells and, consequently, in the development of a wide range of cancers." (PMID 38938528, 2022). "Lactic acids generated by glycolytic tumor cells were reported earlier to drive the pro-tumoral polarization of macrophages via the ERK/STAT3 signaling activation." (PMID 36117852, 2022). "Our results suggest that western blot should always be included for characterize the expression level of STAT3 and phospho-STAT3 (Tyr705) in tumor cell studies." (PMID 35836213, 2022). "Tumor-derived factors such as GM-CSF, CSF-1, and G-CSF signal through signal transducer and activator of transcription 3 (STAT3), CCAAT/enhancer-binding protein β (C/EBPβ) and IRF8 to promote myelopoiesis." (PMID 36031601, 2022). "GzmM expressed in carcinomas has been implicated in promoting tumor growth, metastasis, and EMT dependent on STAT3 signaling." (PMID 35222418, 2022). "Tc9 cells resist tumor- or ROS-induced ferroptosis through the IL-9/STAT3/fatty acid oxidation pathway." (PMID 35192544, 2022). "The JAK2/STAT3 signaling pathway plays a key role in mediating multiple effects of IL-6 on tumor cell proliferation, anti-apoptotic, invasion and metastasis." (PMID 35790790, 2022). "By contrast, inhibitors of STAT3 work by a mechanism distinct from ispinesib—by enabling tumor cells to undergo the mitotic catastrophe that ordinarily follows a G2M block." (PMID 35732128, 2022). "In this case, STAT3, the transcription activator of CPT1a, attenuates the tumoricidal function of Teff cells and promotes tumor progression." (PMID 39872079, 2022). "Many tumor cells that display constitutive STAT3 activation in vivo rapidly lose STAT3 phosphorylation once being placed in a culture medium without neighboring immune or stromal cells." (PMID 35836213, 2022). "Herein, DYRK1A was found to be coexpressed with members of the TGF-β/SMAD and STAT3 signalling pathways in clinical tumour samples from patients with HCC." (PMID 35655269, 2022). "They suggested that the loss of VEGF/VEGFR signalling in tumour cells contributes to the acquired resistance of VEGFR-targeted therapies via activation of c-Met, STAT3, and PI3K/AKT signalling pathways." (PMID 36429091, 2022). "A recent study showed that anti-CD38 antibodies decorated NPs loaded with the STAT3 inhibitor S3I-1757 which possess in vitro STAT3 inhibition and elicit significant improvement in tumor suppression in a xenograft mice model." (PMID 35158821, 2022). "IL-6 stimulates hyperactivation of JAK/STAT3 signaling, which promotes tumor proliferation, angiogenesis, invasiveness, and immunosuppression." (PMID 35136076, 2022).
tumor (continued). "We have recently shown that liver metastasis-derived MDSCs (LM-MDSCs) limit anti-tumor immunity predominantly via a STAT3-mediated mechanism, driven in part by GM-CSF." (PMID 35697801, 2022). "Among all JAK1/STAT pathways, the JAK1/STAT3 pathway is reported to play an important role in the proliferation, apoptosis, migration, and invasion of tumor cells." (PMID 34738874, 2022). "Cytokines released by tumor-infiltrating immune cells motivate key transcription factors NF-κB and signal transducer and activator of transcription 3 (STAT3) that impel cancer progression via chemokine induction." (PMID 36726985, 2022). "As a result, activated STAT3 upregulates proliferation-related factors, leading to excessive proliferation of tumor cells." (PMID 35288541, 2022). "Phosphorylation of STAT3 contributes to the deposition of collagen and release of IL‐10 and IL‐4 in tumours." (PMID 36178087, 2022). "The researchers dug deeper and concluded that resveratrol attenuated the immunosuppression mainly by inhibiting the activation of STAT3 signaling in the tumor." (PMID 36615387, 2022). "Among them, some natural compounds have also shown anti-tumor activity and have demonstrated inhibition of STAT3 in vivo and in vitro experiments." (PMID 36291659, 2022). "STAT3 activation and inactivation are highly regulated in normal cells, whereas in tumor cells, downregulation of the endogenous negative regulators of the STAT3 signaling pathway leads to enhanced proliferation and malignancy." (PMID 36557902, 2022). "In a recent study, the connection between tumor progression and STAT3 driven metabolism was discovered." (PMID 35270020, 2022). "In particular, the IL-6/Stat-3 axis has been described as the main mechanism through which adipocytes induce the EMT phenotype in tumor cells." (PMID 35625629, 2022). "To explore more effective STAT3 inhibiting anti-tumour drug candidates, we synthesised a series of celastrol derivatives and biologically evaluated them with several human cancer cell lines." (PMID 34894961, 2022). "Specifically, Tc9 cell-derived IL-9 can activate STAT3 to increase fatty acid oxidation and mitochondrial activity, which imparts Tc9 cells with reduced lipid peroxidation and the resistance to tumor or ROS-induced ferroptosis." (PMID 36003368, 2022). "In fact, the abrogation of STAT3 in neutrophils enhanced the cytolytic activity of neutrophils and induced tumor regression." (PMID 36010693, 2022). "miR-223 significantly inhibits the differentiation and accumulation of MDSCs as well as their suppressive function by targeting myocyte enhancer factor 2C (MEF2C) and inhibiting STAT3 signaling respectively in tumor-bearing mice." (PMID 36569895, 2022). "Using IB and IHC staining, we also observed that the levels of EGFR, p-AKT, and p-STAT3 were down-regulated in FBXW2-overexpressing tumor tissues of mice model, whereas p21 and p27 were enhanced." (PMID 35499593, 2022). "miR-125b targets multiple genes involved in the regulation of apoptosis, including BAK1 and STAT3, but depending on the cell type, miR-125b can either contribute to oncogenesis or tumor suppression." (PMID 35898539, 2022). "Inhibition of STAT3 activity has become an important way to prevent tumor occurrence and metastasis." (PMID 36371217, 2022). "More interestingly, radotinib inhibited the STAT3-targeted proteins such as Bcl-xl, Mcl-1, c-Myc, and cyclin D3 expression in IM-9 cells isolated from the tumor tissue." (PMID 35503759, 2022). "While STAT3 hyperactivation is largely believed to encourage tumor development and progression, this paradigm is clouded by some data suggesting a tumor suppressor role for STAT3." (PMID 35406557, 2022). "This played a crucial role in tumor growth because it was found that its promotion was embedded with the activation of STAT3 in CAFs in CRC." (PMID 36139552, 2022).
tumor (continued). "Tumor‐derived granulocyte colony stimulating factor (G‐CSF) can also activate the STAT3 pathway in neutrophils and show pro‐tumor effects involving dysfunction of NK cells via PD‐L1/PD‐1 interactions." (PMID 35356799, 2022). "Available data particularly highlight STAT3 activation in neoplastic cell elements consequent to local IL-6 effects as a key determinant of tumor progression and metastasis." (PMID 35406728, 2022). "Previous studies have shown a collaborative interaction between the Wnt- and STAT3-mediated signaling pathways for tumor initiation and metastasis 18, 20-23." (PMID 34987637, 2022). "STAT3 mediates the expression of multiple genes to cell stimuli in tumor cells, thus playing a key role in many cellular processes such as cell growth and apoptosis." (PMID 35744840, 2022). "In CRC, the JAK/STAT3 pathway can directly regulate tumor immune cells and upregulates the expression of oncogenic proteins, such as c-MYC, Cyclin D1, BCL2 or MCL1 to help drive tumor progression and chemoresistance." (PMID 35501324, 2022). "STAT3-miRNAs interactions are emerging as a novel mechanism of malignant tumor regulation reacted in many literatures." (PMID 35541892, 2022). "It inhibits the signaling pathways including Wnt/β-catenin, mTORC1, Stat3, NF-κB, and Notch, but also damages tumor cell mitochondria, inhibits proliferation, and induces apoptosis and autophagy." (PMID 36457117, 2022). "Depending on the model, STAT3 activation was either beneficial or detrimental to the ability to fight the tumor." (PMID 35270020, 2022). "The present study revealed that the high expression of PELP1 is closely related with angiogenesis in CRC.We proved that PELP1 promotes tumor angiogenesis by activating the STAT3 pathway." (PMID 35053547, 2022). "One such potential mechanism governing therapeutic resistance unveiled in the present study is the previously unrecognized role of neutrophil-derived IL-1β in driving iCAF polarization and CAF-tumor cell IL-6/STAT-3 signaling in the PDAC TME." (PMID 36107485, 2022). "Kaplan-Meier univariate analysis showed that tumor differentiation, pN, pTNM, and p-STAT3 were related factors affecting the 5-year survival rate of AEG patients (P < 0.05, P < 0.01, P < 0.05, P < 0.01)." (PMID 36225196, 2022). "Analysis of the GSE database revealed that tumor samples expressed significantly higher levels of STAT3 in HNSCC and CRC, in comparison with normal tissues." (PMID 36509291, 2022). "It has been reported that METTL3 deletion enhances the activation of NF-κB and STAT3 indirectly, leading to tumor growth and metastasis." (PMID 35874897, 2022). "IL-22 induces tumor-elicited inflammation from the T lymphocytes (CD4+ T cells) production via the activation of STAT3." (PMID 35563678, 2022). "Only one published study has proved that in the mouse xenograft model, BCL3 inhibited tumor growth via positively regulating STAT3/p-STAT3 and the downstream targets including cyclin D1." (PMID 35488886, 2022). "For tumor-infiltrated immune cells, STAT3 favors colonization of Tregs and polarization of macrophages towards the M2 phenotype while restricting antigen presentation by DCs and the cytotoxic effects of CD8+ T-cells and NK cells." (PMID 36080223, 2022). "Consistent with our in vitro observations, the expression of activated STAT3 in the tumours of these mice was reduced compared to that in the control group." (PMID 35517401, 2022). "The apoptotic and amplifying activities of this compound are related to the inhibition of JAK/STAT signaling, as it can prevent STAT1 phosphorylation by inhibiting JAK and STAT3, which reduces the activity of antiapoptotic genes and induces tumor cell death." (PMID 36193062, 2022). "It has been demonstrated that STAT3 inhibits the transcription of pro-apoptotic genes in tumor cells through its N-terminal domain." (PMID 35559037, 2022).
tumor (continued). "In light of the ongoing research on STAT3 inhibitors, we also discuss how targeting STAT3 would affect the two arms of STAT3-dependent regulation of NK cell-mediated anti-tumor immunity." (PMID 35865518, 2022). "STAT3 can directly regulate the expression of c-Myc and induce tumor cell apoptosis by regulating c-Myc." (PMID 35113040, 2022). "In line with previously published data, both Smad7-positive cells and p-Stat3-positive cells were more abundant in the tumor tissue, compared to the normal mucosa of CRC patients." (PMID 36291778, 2022). "The inhibition of STAT3 functions is well established to suppress tumor cell viability, growth, survival and migration." (PMID 36473850, 2022). "Studies have also confirmed that STAT3 is upregulated in most cancers and participates in promoting tumor invasion." (PMID 35093120, 2022). "IL-4 and IL-13 are believed to carry out abundant functions in tumour cells through several pro-oncogenic pathways involving signal factors such as STAT3, STAT6, PI3K/Akt, and ERK1/2." (PMID 35409019, 2022). "It has been observed that STAT3 is constitutively activated in many solid and hematological tumors, contributing to cancer initiation and progression, tumor growth, chemoresistance and metastasis." (PMID 35956786, 2022). "Activation of STAT3 signaling pathway resulted in decreased apoptosis and promoted overall tumor growth." (PMID 34875483, 2022). "In conclusion, the present study shows that TRIM47 positively regulates STAT3 signaling, thereby promoting tumor growth and progression." (PMID 36288633, 2022). "Previous studies have found that excessive accumulation of ROS in tumor cells can inhibit the STAT3 signaling pathway." (PMID 36371217, 2022). "STAT3 decoy inhibitors inhibit STAT3 dimerization which is essential for translation into the nucleus to act as a transcriptional factor for a plethora of tumor survival genes." (PMID 35401182, 2022). "Previous investigations have implicated that PTGDS influenced tumor progression by modulating PPARγ, MAPK, and STAT3 pathways." (PMID 34743203, 2022). "Tumor-derived exosomes induce proinflammatory cytokine expression and PD-L1 regulation in M0 macrophages through IL-6/STAT3 and TLR4 signaling pathways." (PMID 36176299, 2022). "Directly, IL-6 binds to its receptor on tumor cells and activates the STAT3 signaling pathway, which will lead to tumor progression through cyclin D1 and the proto-oncogene c-myc, an important regulator of the progression of G1 to S phase of the cell cycle." (PMID 36172343, 2022). "PTPN4 appears to function as a tumor suppressor in cancer, miR-15b-5p activates STAT3 signaling by targeting PTPN4 to promote oral squamous cell carcinoma progression." (PMID 35957898, 2022). "MiR-134-5p, which directly target Stat3, is down-regulated in co-cultured MSCs, leading to tumor-like transformation of MSCs by enhancing Pvt1 expression, representing novel targets for therapeutic intervention of malignant diseases." (PMID 36295083, 2022). "W2014 not only exhibited potent anti-tumor activities but also sensitized drug-resistant NSCLC cells to gefitinib by inhibiting aberrant STAT3 signaling in vitro and in vivo." (PMID 36559280, 2022). "The phosphorylation level of STAT3 and NF-κB in tumor tissues increased with the decrease of circRNA level." (PMID 35139763, 2022). "The relevance of STAT3 in cell plasticity and tumor progression is well established; its activation is controlled in a context-dependent manner by multiple cytokines." (PMID 35993361, 2022). "GBM cells are highly addicted to STAT3 (signal transducer and activator of transcription 3) and STAT3 inhibition blocks GBM-driven tumor growth." (PMID 40396025, 2022). "Intratumoral treatment with formulated STAT3 MCs led to tumor growth inhibition in an orthotopic TNBC mouse model with decreased expression of STAT3 target genes in the tumor, along with a reduction in lung metastasis." (PMID 35847174, 2022).